IDH2 (isocitrate dehydrogenase (NADP(+)) 2)
Diseases named in the same sentence as IDH2 in open-access papers (continued):
Sharing a sentence is not in itself a finding about the gene and the disease.
breast cancer (continued). "Thus, to further understand the requirements of NADPH in 2HG production in breast cancer cells, we overexpressed IDH2 mutant R172K, which produces excessive levels of 2HG while still requiring NADPH as a cofactor." (PMID 33916579, 2021). "Furthermore, publicly available gene expression databases identified high levels of IDH2 expression in prostate, testis, eye, nervous system, and breast cancers." (PMID 31010244, 2019). "Our data suggested G6PD, IDH1 and IDH2 may carry out a novel mechanism with adriamycin resistance in breast cancer." (PMID 25818003, 2015). "Hence, we evaluated 2HG levels in several breast carcinoma cultured cell lines, derived from primary and secondary tumors and we demonstrated that 2HG is actively formed by IDH2 and ADHFE1 and that there is a competition between these two enzymes, which regulate substrate flux in mitochondria." (PMID 33916579, 2021). "In summary, our study revealed a novel post-transcriptional regulation of IDH2 protein by the E3 ligase RNF185, and illustrated the function of D-mannose on regulating RNF185-IDH2 axis to inhibit the proliferation of breast cancer cells." (PMID 38167476, 2024). "Our study demonstrated that D-mannose can degrade IDH2 and inhibit the production of NADPH to suppress the proliferation of breast cancer cells and render the breast cancer cells more sensitive to pro-oxidant treatment." (PMID 38167476, 2024). "IDH2, an NADPH-generating enzyme, was identified as an SIRT-5 substrate in mammary tumors: SIRT-5 was demonstrated to desuccinylate and activate IDH2." (PMID 36080416, 2022). "Real-time quantitative PCR validation of RNA-seq data was done for IDH2, ID1, KRT80, and CALCR genes both in circNFATC3 silenced MDA-MB-231 breast cancer cells and SK-OV-3 ovarian cancer cells." (PMID 33816459, 2021). "The expression of IDH2 protein in normal and breast cancer tissues (including TNBC and non-TNBC tumor samples) was analyzed using immunohistochemistry staining." (PMID 38658533, 2024). "Consequently, IDH2-mediated NADPH production was inhibited by D-mannose, the proliferation of breast cancer cells was retarded, and the sensitivity to pro-oxidant of breast cancer cells was elevated." (PMID 38167476, 2024). "IDH1 protein content is not deferentially expressed between breast cancer cells compared to IDH2." (PMID 39195531, 2024). "Therefore, there is a substantial negative connection between IDH2 Lys413 acetylation and breast cancer risk and SIRT3 regulates the progression of breast cancer and the metabolism of breast cancer cells by mediating IDH2 dimerization." (PMID 35571098, 2022). "Indeed, sterol response element-binding protein 1 (SREBP1) has been demonstrated to regulate hBCATm, in pancreatic ductal adenocarcinoma and IDH1, but not IDH2 expression, in breast cancer." (PMID 33367952, 2021). "Utlising tissue microarrays from a large well annotated BC cohort including ductal carcinoma in situ and invasive breast cancer (IBC), IDH2 was assessed at the transcriptomic and proteomic level." (PMID 31599393, 2020). "Also, estrogen receptor-negative (ER−) breast carcinoma HTB-126/Hs 578T cells, and epithelial adenocarcinoma MDA-MB-231 cells, contain 2HG in the absence of IDH2 mutations and its formation substantially dropped upon IDH2 silencing." (PMID 31847543, 2020). "However, the prognostic significance of IDH2 in breast cancer has not been described before." (PMID 31599393, 2020). "However, we and others have previously demonstrated that wild-type IDH2 (IDH2 WT) produces 2HG in breast cancer cells; i.e., in HTB-126/Hs578T cells, 2HG is readily formed in the absence of known IDH2 mutations, and IDH2 WT was identified to be responsible for its substantiate part." (PMID 32457458, 2020).
breast cancer (continued). "However, even wild-type IDH1 and IDH2, notably under shifts toward reductive carboxylation glutaminolysis or changes in other enzymes, lead to “intermediate” 0.01–0.1 mM 2HG levels, for example, in breast carcinoma compared with 10−8M in noncancer cells." (PMID 31847543, 2020). "The role of necroptosis-related genes in breast cancer, such as FASLG, FLT3, HSPA4, IDH2, IPMK, LEF1, and SLC39A7, has not been extensively studied, and these necroptosis-related genes have been confirmed to regulate the biological processes of necroptosis in various types of tumors." (PMID 36675706, 2022).
melanoma (32 papers, 2013 to 2025). A malignant, usually aggressive tumor composed of atypical, neoplastic melanocytes. "Most recently, Lian and colleagues reported that loss of 5 hmC is an epigenetic hallmark of melanoma, and IDH2 and TET family are directly linked to this process." (PMID 24427299, 2014). "Genome-wide mapping of 5-hydroxymethylcytosine revealed its loss in melanoma, and restoring active TET2 or IDH2 reactivated 5-hydroxymethylcytosine suppressed melanoma growth and increased tumor-free survival in animal models, suggesting the therapeutic potential of targeting epigenetic changes." (PMID 31888295, 2019). "Indeed, it was demonstrated that tumorigenesis of B16F10 melanoma cells was strongly reduced when cells are implanted in IDH2-deficient (IDH2−/−) mice." (PMID 31010244, 2019). "Significantly, the WEE1 inhibitor AZD1775 not only abrogated the suppressive H2B Y37-phosphorylation and upregulated IDH2 mRNA levels but also effectively reversed the ‘loss of 5-hmC’ phenotype in melanomas, GBMs and prostate cancer cells, as well as melanoma xenograft tumors." (PMID 29290954, 2017). "Importantly, overexpressing IDH2 or TET2 restored 5-hmc levels in melanoma cell lines, suggesting that lack/loss of function of these enzymes plays an essential role in 5-hmc depletion during melanoma progression." (PMID 28396701, 2017). "In-depth analysis of melanoma’s epigenomic landscape uncovered a comprehensive loss of 5hmC, and the reintroduction of active TET2 or isocitrate dehydrogenase 2 (IDH2) in melanoma cells restored the 5hmC landscape and suppressed melanoma growth." (PMID 39519332, 2024). "Isocitrate dehydrogenase (IDH2) is one of the key enzymes in melanoma’s antioxidant system, and downregulation of IDH2 has been shown to inhibit tumor growth." (PMID 37297001, 2023). "Upregulation of additional genes from the bile acid and peroxisome signaling pathways was also evident in TIL gene and pathway expression analysis, including upregulation of SOD1, ACSL5, FADS2, CAT, DHCR24, SLC27A2, and IDH2 in melanoma TILs compared to pCD8s." (PMID 38023136, 2023). "Decrease in mitochondrial dependence in melanoma DC was closely associated with significant reduction in scMEP OXPHOS markers CytC, ATP5A and IDH2." (PMID 37938561, 2023). "Again, IDH2 amplification was seen particularly in prostate adenocarcinoma, pancreatic adenocarcinoma, melanoma, and invasive breast carcinoma." (PMID 34440884, 2021). "Rebuilding the 5-hmC landscape in melanoma cells by reintroducing active TET2 or IDH2 suppressed melanoma growth and increased tumor-free survival in animal models." (PMID 34198758, 2021). "The same study showed that 5hmC levels were also low in melanoma cells, and restoration of 5hmC by ectopic expression of IDH2 or TET2 suppressed melanoma growth and increased tumor-free survival in animal models." (PMID 33024276, 2020). "Downregulation of IDH2 and TET family enzymes is one of the main mechanisms responsible for 5-hmC loss in melanoma." (PMID 29156643, 2017). "These indicated that the melanoma patients whose IDH2/Actin ratios are <1.8, are likely to have active/elevated WEE1/pY37-H2B signaling." (PMID 29290954, 2017). "This approach was particularly interesting for connecting the melanoma cell lines with the reverse flux through the IDH2 and psydohypoxia." (PMID 28806730, 2017). "The differences in relative IDH2 mRNA levels between melanoma and primary human keratinocyte were statistically significant (p = 0.048)." (PMID 29290954, 2017). "Consistently, GBMs and primary melanoma tumors that display elevated WEE1 mRNA expression exhibit significant down regulation of the IDH2 gene transcription." (PMID 29290954, 2017). "Downregulation of the enzymes involved in hmC production—isocitrate dehydrogenase 2 (IDH2) and Ten-eleven Translocation (TET) family enzymes—is a main mechanism responsible for hmC loss in the melanoma epigenome." (PMID 29156643, 2017).
melanoma (continued). "In fact, inhibition of wild-type IDH2 would be advantageous in some cancers, such as melanoma, which rely on IDH2-mediated oxidative decarboxylation to maintain proper redox balance in mitochondria." (PMID 28649560, 2017). "Although melanoma cells seem to rely on IDH2 activity to maintain proper mitochondrial redox balance, most other types of cancer cells depend on IDH2 for reductive carboxylation." (PMID 28649560, 2017). "A significant decrease in IDH2 mRNA expression profile was apparent in melanomas as compared to normal skin samples or primary human keratinocyte derived cell line." (PMID 29290954, 2017). "In melanoma, IDH2 is frequently downregulated, and the overexpression of IDH2 in a zebrafish melanoma model has been shown to increase the level of 5-hmC, resulting in prolonged tumor-free survival." (PMID 24716838, 2014). "Reintroducing active TET2 or IDH2 was found to suppress melanoma growth and increase tumor-free survival in animal models." (PMID 23533770, 2013). "In melanoma, down-regulation of TET, especially TET2, and IDH2 transcripts have been reported as mechanisms of 5-hmC loss." (PMID 24202321, 2013). "This is supported by the fact that restoring TET2 expression slows melanoma cell growth in mice xenografts and overexpression of IDH2 in a zebrafish model of melanoma improves tumor-free survival." (PMID 24202321, 2013). "Ten percent of melanomas (4/39) harbor IDH1 or IDH2 mutations, while no TET mutation has been reported in these tumors." (PMID 34198758, 2021). "To date, no FDA-approved drugs or clinical trials are available for melanoma patients carrying IDH1/IDH2 mutations." (PMID 32850962, 2020). "Specifically, IDH2 was significantly downregulated in melanomas as compared with nevi." (PMID 31010244, 2019). "IDH2 knockdown also increases the sensitivity of melanoma cells to the ROS-inducer compound emodin." (PMID 28649560, 2017). "Consistent with this notion, in melanoma cells, which in most cases do not carry IDH2 mutations, knockdown of this gene decreases the mitochondrial NADPH/NADP+ ratio, increases ROS levels, and impairs tumorigenicity in vivo." (PMID 28649560, 2017). "Overall, our data reveal a novel mode of WEE1 mediated IDH2 downregulation as a recurrent epigenetic alteration that may be operational in melanomas, GBMs and prostate cancers." (PMID 29290954, 2017). "Importantly, the expression of active TET2 or IDH2 into melanoma cells restores the 5-hmC landscape, inhibits melanoma proliferation, and increases survival in animal models." (PMID 29156643, 2017). "Restoring 5-hmc levels by IDH2 and TET2 overexpression was associated with suppressed tumor invasion and growth in a zebrafish melanoma model and mouse xenograft model of melanoma, suggesting a potential functional role of this epigenetic mark in melanoma growth and invasion." (PMID 28396701, 2017). "Thus, the data supported a prevalence of IDH2 for normal skin cell types, skin cancers, and melanoma at the protein level." (PMID 28806730, 2017). "Moreover, 4 of 7 melanoma patients with WT BRAF too exhibited significant downregulation of IDH2 levels." (PMID 29290954, 2017). "Based on our simulations, a reverse flux through IDH2 was required in some of the melanoma models." (PMID 28806730, 2017). "Interestingly, the five melanoma cell lines WM1963, IPC298, WM1396, WM3918, SK-MEL-2 that do not possess V600E mutation responded well to the WEE1 inhibitor, increasing IDH2 mRNA and 5-hmC levels." (PMID 29290954, 2017). "In melanoma, loss of 5mC through oxidation to 5hmC has been observed both as a result of IDH1 or IDH2 neomorphic mutations as well as the downregulation of TET and IDH2 genes." (PMID 24705290, 2014). "In addition to BRAF WT melanomas, IDH2 levels were also assessed in BRAF V600E mutant melanomas." (PMID 29290954, 2017).
melanoma (continued). "Furthermore, mutations in IDH1 or IDH2 genes have not been identified in melanomas, but still, virtually all malignant melanoma samples exhibited either a partial or complete loss of 5-hmC." (PMID 29290954, 2017). "Absence of IDH1 and IDH2 mutations in the melanoma (or low occurrence in GBMs) indicates that these mutations are unlikely to be the major determinants promoting a loss of 5-hmC in melanomas, primary GBMs and prostate cancers." (PMID 29290954, 2017). "Additionally, IDH2 downregulation decreased growth, angiogenesis, and increased apoptosis in tumors formed by melanoma cells injected into mice as compared to IDH2 wild-type melanoma cells." (PMID 28806730, 2017). "In turn, melanoma expresses MCT2, LDHB, and IDH2 to take up lactate and convert it to pyruvate to be used in the TCA cycle." (PMID 41463339, 2025). "One study showed that IDH2 and TET1 expression was reduced in melanoma compared with that in melanocytic naevi." (PMID 33024276, 2020). "The significance of 5-hmC loss specifically in cancer cells became further evident when reintroduction of the 5-hmC by recombinant IDH2 or TET2, suppressed tumor growth and increased tumor-free survival in the melanoma mouse models." (PMID 29290954, 2017). "To address this supposition, we examined the mRNA levels of WEE1, IDH2 and Actin (control) in melanoma and GBM tumors and observed that these patients exhibited elevated WEE1 mRNA expression and a significant down regulation of IDH2 transcription." (PMID 29290954, 2017). "Accordingly, IDH2 or TET2 reintroduction in melanoma cells restores the 5-hmC landscape, suppresses melanoma growth, and increases tumor-free survival (TFS) in a zebrafish melanoma model." (PMID 31010244, 2019). "The analysis of protein and RNA expression levels from the Human Protein Atlas showed that IDH2, which was an essential gene in the melanoma models, but not IDH1 protein, was detected in normal skin cell types and melanoma." (PMID 28806730, 2017). "In addition, the decreased expressions of IDH2 and TET2 are responsible for the decreased 5 hmC and restoration of IDH2 or TET2 suppresses melanoma growth and increases tumor-free survival in animal models." (PMID 23671639, 2013). "The frequency of mutations in the genes is consistent with that reported in the literature for IDH1 and IDH2 in brain tumors, EGFR and KRAS in NSCLCs, KRAS and NRAS in CRCs, BRAF, RAS, PIK3CA, and TERT in thyroid nodules, BRAF, NRAS and cKIT in melanoma, and KRAS in pancreatic pre-operative samples." (PMID 32340363, 2020). "In support of this in silico result, IDH2 but not IDH1 expression could be measured on the protein level in normal skin cells and melanoma." (PMID 28806730, 2017). "Thus, the experimental data supported the predicted role of IDH2 and the absence of VHL protein supported the glycolytic and low oxygen phenotype predicted for melanoma." (PMID 28806730, 2017).
myelodysplastic syndrome (32 papers, 2010 to 2025). A clonal hematopoietic disorder characterized by dysplasia and ineffective hematopoiesis in one or more of the hematopoietic cell lines. "Both IDH1 and IDH2 gene mutations are found in approximately 20% of AML as well as 12% of myelodysplastic syndrome (MDS) especially in high-risk cases." (PMID 35216478, 2022). "IDH1/IDH2 mutations increase the risk of transformation from myelodysplastic syndrome (MDS) to high-risk AML and are associated with poor prognosis in AML, underscoring their role in disease progression." (PMID 41295305, 2025). "Finally, gain-of-function mutations in the IDH1 and IDH2 genes have been found in a small number of individuals with myelodysplastic syndromes (MDS) and MPNs." (PMID 40699626, 2025). "IDH2 mutations in lower frequencies have also been identified in other malignant tumors, including myeloproliferative neoplasms (MPN) and myelodysplastic syndromes (MDS)." (PMID 33981605, 2021). "Genes that regulate DNA methylation and demethylation (e.g., DNMT3A, IDH1 and IDH2, TET2) are commonly mutated in adult AML and myelodysplastic syndromes (MDS), although the frequency of these mutations appears much lower in pediatric AML." (PMID 24672775, 2014). "Genome sequencing has also revealed the presence of metabolic mutations in patients with myelodysplastic syndromes (MDS) and AML related to the isocitrate dehydrogenase (IDH) 1 and IDH2 genes." (PMID 23533770, 2013). "IDH1 and IDH2 have been reported to be frequently mutated in AML, Myelodysplastic Syndromes (MDS) and chronic Myeloproliferative Neoplasms (MPNs), the most frequent mutations being single-nucleotide variants involving the exon 4 at the arginine hotspot R140 or R172." (PMID 35741115, 2022). "The only clinical trial currently that accepts pediatric AML patients is investigating the synergistic effect of azacytidine and enasidenib in myelodysplastic syndrome (MDS) with IDH2 mutation (NCT03383575), whereas there is no ongoing trial in pediatric AML yet." (PMID 36147798, 2022). "Preliminary results were presented on the first 16 treated patients with IDH2-mutated AML and myelodysplastic syndrome (MDS) who initiated enasidenib maintenance therapy 30 to 90 days after allo-HCT for up to twelve 28-day cycles." (PMID 36016625, 2022). "Intriguingly, IDH1 and IDH2 mutations were also found in other myeloid disorders such as myeloproliferative neoplasms (MPN) and myelodysplastic syndrome (MDS) which have a propensity to AML development, although at a much lower frequency than AML." (PMID 22397365, 2012). "Recent genomic sequencing efforts have identified a number of recurrent mutations in myelodysplastic syndromes (MDS) that may contribute to disease progression and overall survival, including mutations in isocitrate dehydrogenases 1 and 2 (IDH1 and IDH2)." (PMID 24936872, 2014). "Differently from myelodysplastic syndrome (MDS), their efficacy in AML is independent of the mutational status of epigenetic modifiers such as IDH1, IDH2, DNMT3A and TET2." (PMID 34439275, 2021). "Meanwhile in 2009, IDH1 mutation was reported in a subset of AML patients lacking specific chromosomal aberrations and in 2010, IDH2 mutation was identified in AML, myelodysplastic syndrome (MDS), and myeloproliferative neoplasms (MPN)." (PMID 22397365, 2012).